TMEM51 (transmembrane protein 51)
Synonyms: C1orf72; FLJ10199
Tractability: Antibody: UniProt predicts a signal peptide or a membrane-spanning region. PROTAC: ubiquitination databases record sites on it.
Gene: Protein-coding gene on chromosome 1 (15,152,498 to 15,220,484, forward strand). Ensembl gene ENSG00000171729.
Subcellular location: Membrane
Subcellular location (Human Protein Atlas): Cytosol; Nucleoplasm
Gene Ontology:
Molecular function: protein binding
Cellular component: membrane
Genetic constraint (gnomAD): Loss-of-function variants: 8 observed, 16.57 expected, observed/expected ratio (o/e) 0.48, 90% interval 0.28 to 0.87. The upper end of that interval is the gene's LOEUF score, 0.87, which puts it in group 3 of 6, group 1 being the genes least tolerant of losing a copy. Missense variants: 279 observed, 344.42 expected, observed/expected ratio (o/e) 0.81, 90% interval 0.73 to 0.89. Synonymous variants: 147 observed, 149.19 expected, observed/expected ratio (o/e) 0.99, 90% interval 0.86 to 1.13.
Homologues: Orthologues: chimpanzee TMEM51 (100% identical), macaque TMEM51 (98% identical), pig TMEM51 (90% identical), dog TMEM51 (89% identical), rat Tmem51 (87% identical), guinea pig TMEM51 (86% identical), mouse Tmem51 (85% identical), rabbit TMEM51 (81% identical), tropical clawed frog tmem51 (50% identical), zebrafish tmem51b (37% identical), zebrafish tmem51a (32% identical).
Diseases named in the same sentence as TMEM51 in open-access papers:
TMEM51 is named in the same sentence as 4 diseases in open-access papers, as found by Europe PMC text mining. Sharing a sentence is not in itself a finding about the gene and the disease. The quoted sentences say what the papers report.
cancer (3 papers, 2018 to 2025). A tumor composed of atypical neoplastic, often pleomorphic cells that invade other tissues. "When comparing NACT-treated samples with untreated ones in cancer patients the expression of TMEM51, NOTCH1, EEPD1, MAFB, and HLA-DRB5 remained increased in monocytes of treated patients." (PMID 39315092, 2024). "In BC tissues, TAP1, PILRA, UBE2C, TMEM51, and MKI67 were significantly upregulated, while the expression levels of SPP1 and CENPF remained unchanged between cancer and adjacent tissues." (PMID 41328437, 2025).
hematological malignancies (1 paper, 2022). "To date, PTBP2, TMEM51, and MTOR have been found as fusion partners of KAZN by RNA sequencing studies in solid tumors, while, as far as we know, rearrangements of KAZN have never been described in hematological malignancies." (PMID 34859285, 2022).
TMEM51 also shares sentences with these, for which no sentence is quoted: tumor (3 papers); asthma (1).